VDR (vitamin D receptor)
Diseases named in the same sentence as VDR in open-access papers (continued):
Sharing a sentence is not in itself a finding about the gene and the disease.
vitamin D deficiency (continued). "Liver disease has also been strongly linked to vitamin D deficiency, and the development of the vitamin D receptor (VDR) knockout (VDRKO) murine model has greatly increased our understanding of vitamin D’s role in the liver." (PMID 29659559, 2018). "Studies have shown that glucose induced insulin secretion is impaired by knocking out vitamin D receptor and by inducing vitamin D deficiency." (PMID 29320437, 2018). "Several single nucleotide polymorphisms have been described in the VDR gene which are supposed to affect metabolic disorders related to vitamin D deficiency." (PMID 30166978, 2018). "Decreased expression of CYP27B1 and VDR, which we established, is most likely a consequence of vitamin D deficiency and inadequate production of the 25OHD prohormone in the liver of diabetic animals." (PMID 29552033, 2018). "Other authors showed that vitamin D deficiency contributed to the losses of muscle mass and strength, which is related to a reduction of vitamin D receptors (VDR) in muscles." (PMID 29743982, 2018). "This is surprising given that vitamin D deficiency has been associated with muscle myopathy and weakness, and vitamin D receptor activation by vitamin D has been shown to increase muscle protein synthesis." (PMID 29394922, 2018). "On the other hand, we previously showed that vitamin D deficiency caused a decrease in VDR expression and an increase in TGF-β expression in a model of CKD progression." (PMID 30370270, 2018). "Among Afro-American women, vitamin D deficiency because of higher melanin concentrations results in decreased serum vitamin D levels and reduced expression of the vitamin D receptor (VDR) in the adjacent myometrium, compared to white women." (PMID 30011902, 2018). "Further studies with vitamin D receptor (VDR) knockout mice extrapolated a functional link between vitamin D deficiency, elevated FOXO1 and insulin resistance in muscle cells." (PMID 30558244, 2018). "There is evidence that vitamin D deficiency or VDR polymorphism are associated with increased risk of chronic periodontitis." (PMID 29951549, 2018). "Animal models with tissue-specific VDR deletion circumvent the problem of pleiotropic effects of vitamin D signalling, and the endocrinological disorders linked to vitamin D deficiency." (PMID 30273386, 2018). "The presence of the vitamin D receptor, 1α-hydroxylase, and vitamin D-binding protein in the hypothalamus suggests a role of vitamin D deficiency in the generation of various primary headache disorders." (PMID 30019090, 2018). "The presence of VDR in most of the tissues provides a mechanistic link between vitamin D deficiency and the pathophysiology of the disorders." (PMID 30296271, 2018). "The hypocalcemic phenotype shared by vitamin D deficiency and VDR knockout models can be reversed by a high-calcium diet, but even at very low levels of 1,25(OH)2D3, the VDR can still operate in a ligand-independent modality or can respond to other molecules." (PMID 29874855, 2018). "The widespread consequences of vitamin D deficiency have been partly attributed to the ubiquitous distribution of the vitamin D receptor." (PMID 29415666, 2018). "Maternal vitamin D deficiency was found in all pathological pregnancies combined with significantly reduced staining levels of placental VDR in IUGR." (PMID 30408071, 2018). "Association between VDR BsmI and risk of vitamin D deficiency in Malaysian adolescents presented as OR (unadjusted and adjusted) with 95% CI." (PMID 28617856, 2017). "Risk of vitamin D deficiency, obesity and insulin resistance with A allele of VDR BsmI compared to G allele in Malaysian Adolescent Population presented as OR (unadjusted and adjusted) with 95% CI." (PMID 28617856, 2017). "Rare alleles for all four of the main variants for the VDR gene have been associated with lower serum 25(OH)D concentration and vitamin D deficiency in a range of populations." (PMID 28976930, 2017).
vitamin D deficiency (continued). "As vitamin D presents immunosuppressive effects and there are potential link between vitamin D deficiency and autoimmune diseases, VDR polymorphisms that can affect VDR activity, have been evaluated as the probable cause of autoimmune diseases." (PMID 29280010, 2017). "According to the findings in addition to vitamin D deficiency, the vitamin D receptor (VDR) polymorphisms can confer susceptibility to immune-related diseases such as rheumatoid arthritis (RA) and systemic lupus erythematous (SLE)." (PMID 29280010, 2017). "Detailed investigation into mechanisms behind ligand-independent cytoplasmic activity of VDR under conditions of vitamin D deficiency would have clinical applicability in deciding the treatment strategies in patients with breast cancer." (PMID 28460457, 2017). "We found that adolescents carrying the AA genotype of VDR BsmI were associated with increased risk of both vitamin D deficiency and insulin resistance compared to the GG genotype." (PMID 28617856, 2017). "VDR knock-out mice show the full phenotype of severe vitamin D deficiency, indicating that VDR is the major mediator of VitD action." (PMID 28423519, 2017). "Results from humans, animals and in vitro studies indicated that vitamin D deficiency increases serum cholesterol levels by reducing VDR activity." (PMID 28811597, 2017). "In comparison with many other cells and tissues that harbor VDR, muscles are one of the most sensitive tissues that vitamin D deficiency causes weakness and fatigue." (PMID 29280010, 2017). "Literature shows that there is a high correlation between vitamin D deficiency, VDR dysfunction, gut microbiota composition, and autoimmune diseases." (PMID 28066436, 2016). "The reduction in VDR expression with vitamin D deficiency was more pronounced in the soleus muscle (−57%) compared with the EDL muscle (−37%; interaction term P<0.05)." (PMID 26906744, 2016). "Vitamin D deficiency and vitamin D receptor gene polymorphisms are known to be significantly associated with high myopia." (PMID 27435453, 2016). "The vitamin D receptor (VDR) mediates the immunological function of vitamin D3, which activates macrophages, and vitamin D deficiency has been linked to tuberculosis risk." (PMID 27595605, 2016). "Experimental studies have postulated an important link between vitamin D deficiency and retinopathy and an increased risk of diabetic retinopathy has been demonstrated in the presence of VDR polymorphisms." (PMID 26885530, 2016). "Taking a step further, the current study was concerned with the gene polymorphism of the VDR being the most widely studied genetic factor implicated in vitamin D deficiency." (PMID 27336155, 2016). "The VDR is abundantly expressed in both intestinal and all immune cells, with several lines of evidence implicating vitamin D deficiency, or downregulation of the VDR, in the pathogenesis and severity of experimental IBD." (PMID 27531998, 2016). "Since vitamin D acts through its binding to VDR, suboptimal responsiveness of the VDR can be manifested as vitamin D deficiency." (PMID 27309378, 2016). "Both vitamin D deficiency and genetic variants in the vitamin D receptor (VDR) have been reported to associate with delayed response to intensive-phase therapy for pulmonary tuberculosis." (PMID 26193879, 2015). "In the present study, we confirmed that vitamin D deficiency, as well as the decreased local expression of vitamin D receptor (VDR), was prevalent in an IBD cohort." (PMID 25813397, 2015). "An effect of vitamin D deficiency on a variety of diseases is biologically plausible because the vitamin D receptor is expressed in a large number of tissues and on several immune cells." (PMID 25954901, 2015). "VDR is observed in human adipocytes, and vitamin D deficiency is capable of up-regulating parathyroid hormone, thereby increasing free intracellular calcium in adipocytes, which blunts the lipolytic response to catecholamines and enhances lipogenesis." (PMID 26177638, 2015).
vitamin D deficiency (continued). "So, analyzing the results, we observed that vitamin D deficiency caused a decrease in VDR expression and an increase in TGF-β expression in VDD+IRI group, which had the highest ratio of fibrosis." (PMID 25222475, 2014). "We observed that vitamin D deficiency caused a decrease in VDR expression and an increase in TGF-β expression in VDD+IRI group, which had the highest ratio of fibrosis." (PMID 25222475, 2014). "We determined the association of vitamin D deficiency and the FokI polymorphism of the vitamin D receptor (VDR) gene in 760 patients who underwent angiography due to suspected coronary artery disease (CAD)." (PMID 24729966, 2014). "An established symptom of vitamin D deficiency is proximal skeletal muscle weakness, caused by reduced stimulation of the cellular Vitamin D Receptor (VDR)." (PMID 24736600, 2014). "This study examined the cardiovascular effects of dietary vitamin D deficiency and of vitamin D receptor agonist (paricalcitol) administration in apolipoprotein E knockout mice." (PMID 24586387, 2014). "Stronger genetic associations with prostate cancer risk were observed for VDR variants among men with vitamin D insufficiency or low sun exposure." (PMID 25368842, 2014). "The severe phenotype of VDR−/− mice makes it difficult to translate accompanying cardiovascular findings to clinical associations of mild vitamin D deficiency/insufficiency." (PMID 24586387, 2014). "Because patients with pancreatic cancer have a high prevalence of vitamin D deficiency in general, patients with lower VDR expression would have poorer prognoses as well as poorer responses to chemotherapy as a result of their vitamin D deficiencies." (PMID 24011168, 2013). "Vitamin D deficiency and vitamin D receptor (VDR) gene polymorphism, FokI, is reported to increase the risk of many cancers." (PMID 23705897, 2013). "The discovery of the vitamin D receptor enabled further investigations on the association of acute and chronic diseases with vitamin D deficiency." (PMID 24967240, 2013). "In the T helper cell type-2 (Th2) response prone BALB/c mouse, vitamin D deficiency reduced the expression of the vitamin D receptor (VDR) in the lungs of mice with allergic airway disease." (PMID 23826346, 2013). "The increased risk of ovarian cancer in combined vitamin D deficiency and vitamin D receptor polymorphism is expected to be due to modulation of same target molecules." (PMID 23705897, 2013). "The human vitamin D receptor (VDR/NR1I1) has been in the focus of research for over a decade, a main reason being a wide spectrum of known effects of vitamin D deficiency." (PMID 22523693, 2012). "The majority of the animal studies that have examined effects on neuronal function have been based on vitamin D receptor knock-out models or developmental vitamin D deficiency." (PMID 22848531, 2012). "Are those at greatest risk for vitamin D deficiency somehow protected by selective differences in vitamin D binding protein affinities and in the vitamin D receptor itself?" (PMID 22666547, 2012). "A similar disparity has been observed in studies investigating the role of VDR deletion versus dietary vitamin D deficiency in the development of diabetes and MS." (PMID 22007288, 2012). "Vitamin D insufficiency, and gene polymorphisms in the vitamin D receptor (VDR) and vitamin D binding protein (VDBP) have been implicated in susceptibility to infectious and chronic diseases." (PMID 23185470, 2012). "Here, we investigated the expression of TNF-α and VDR in post-angioplasty coronary artery neointimal lesions of hypercholesterolemic swine and examined the effect of vitamin D deficiency on the development of coronary restenosis." (PMID 22880111, 2012). "Accordingly, vitamin D deficiency and/or impairment of the vitamin D receptor is linked to abnormalities in bone development, hair growth, cell cycle, immune system function, glucose homeostasis and cardiovascular health." (PMID 22136443, 2011).
vitamin D deficiency (continued). "In accord with this notion, a recent study demonstrated that decreased vascular endothelial cell expression of VDR and 1-α-hydroxylase due to vitamin D deficiency is associated with vascular endothelial dysfunction." (PMID 22114787, 2011). "Children and animals with vitamin D deficiency or VDR mutations have expanded growth plates, known as rickets, which are largely corrected by high calcium diet." (PMID 21695192, 2011). "Whereas detrimental effects of vitamin D deficiency on bone growth have been known over a century, the direct effects of VDR activation on the growth plate are still a matter of investigation." (PMID 21695192, 2011). "Whereas detrimental effects of vitamin D deficiency are known over century, the effects of vitamin D receptor activation by 1,25(OH)2D3, the principal hormonal form of vitamin D, on the growing bone and its growth plate are less clear." (PMID 21695192, 2011). "VDR dysfunction causes alopecia in knockout models and hereditary vitamin D‐resistant rickets patients, while VDR polymorphisms and reduced expression correlate with treatment variability in alopecia areata and androgenetic alopecia, and vitamin D deficiency associates with telogen effluvium." (PMID 41473843, 2026). "Vitamin D deficiency, compounded by genetic factors affecting vitamin D receptor function, lower supplementation rates, and darker skin pigmentation may further impair calcium absorption and bone strength, exacerbating fracture risk." (PMID 40091905, 2025). "Studies indicate that the vitamin D receptor (VDR) directly modulates mitochondrial oxidative phosphorylation capacity in muscle, and vitamin D deficiency markedly decreases the activity of mitochondrial complex I and inhibits critical genes involved in mitochondrial biogenesis." (PMID 40507924, 2025). "For example, VDR expression in melanocytes and melanoma cells suggests a direct influence on tumor growth and immune evasion, and there is evidence from some epidemiological studies linking vitamin D deficiency to worse cancer prognosis." (PMID 40943440, 2025). "Vitamin D deficiency is thought to be associated with decreased expression of the vitamin D receptor and epithelial barrier proteins E-cadherin and claudin-2, which play an important role in children with CeD in correlation with histological indicators of disease severity." (PMID 40837675, 2025). "Obesity not only exacerbates vitamin D deficiency but may also affect vitamin D metabolism through genetic variations in the vitamin D receptor (VDR) gene." (PMID 40710009, 2025). "Vitamin D deficiency may also influence the regulation of VDR expression, disrupting adipocyte metabolism and promoting further fat accumulation." (PMID 40871724, 2025). "The salivary glands also express a vitamin D receptor (VDR), indicating that vitamin D deficiency might reduce salivary flow rate." (PMID 41324716, 2025). "The authors conclude that excessive UV exposure may cause a decrease in VDR gene expression, as may vitamin D deficiency, and that possible VDR polymorphisms may also reduce the effects of vitamin D on target tissues." (PMID 40507396, 2025). "Potential mechanisms by which vitamin D deficiency could influence cardiac events include alterations in calcium-handling proteins and ion channels via the VDR, which is expressed in cardiomyocytes." (PMID 40441193, 2025). "Direct effects of vitamin D depletion or VDR deletion have been demonstrated in vitro and in pre-clinical studies; for example, deletion of the VDR in cardiomyocytes causes myocardial hypertrophy and fibrosis and vitamin D deficiency in chicks and rats produced myocardial dysfunction." (PMID 40448712, 2025). "In addition, several studies, which investigated the effect of vitamin D deficiency in different experimental models of renal injury, showed a decrease in VDR expression." (PMID 40709990, 2025).
vitamin D deficiency (continued). "Vitamin D deficiency and the vitamin D receptor (VDR) FokI polymorphism may suggest independent risk factors for susceptibility to COVID-19 in the pediatric population." (PMID 38947671, 2024). "Individuals with these specific VDR SNPs may be more prone to experiencing higher rates of hypovitaminosis D. Moreover, we hypothesize that vitamin D deficiency, linked to the VDR SNPs, correlates with increased severity of atopy." (PMID 38397449, 2024). "Specifically, the discovery of the vitamin D receptor (VDR) in human skeletal muscle cells and the potential roles of vitamin D in muscles as regards regulating protein synthesis have led to much interest in analyzing vitamin D deficiency in athletes." (PMID 38921847, 2024). "Vitamin D deficiency (aOR = 3.311, 95% CI: 1.584–6.921, p = 0.0010) was significantly associated with a three-fold increase in preeclampsia risk, whilst VDR gene variants, particularly the "bb" genotype (cOR = 0.227, 95% CI: 0.055–0.944, p = 0.0410) was associated with reduced risk of PE." (PMID 38814968, 2024). "We hypothesized that vitamin D deficiency is associated with AS and DS, and the presence of the VDR gene polymorphism (rs2228570) FokI has an interactive effect on this association." (PMID 38519539, 2024). "Our results point to SIRT1 as a critical effector of 1,25(OH)2D3 and rise the hope that acting on SIRT1 may circumvent 1,25(OH)2D3 unresponsiveness derived from vitamin D deficiency or VDR loss as it is common in advanced CRC." (PMID 39494323, 2024). "Furthermore, a study of healthy individuals showed a significant downregulation of the vitamin D receptor in monocytes of individuals with vitamin D deficiency compared with those who had normal vitamin D levels." (PMID 39420939, 2024). "This study was conducted in Brazil to explore whether the VDR gene polymorphism FokI (rs2228570) influences the association between vitamin D deficiency, AS, and DS in adults." (PMID 38519539, 2024). "Using the CC genotype as a reference point, there was no notable variation in GDM risk was observed across different FokI VDR genotypes, even after adjusting for vitamin D deficiency, HbA1c, fasting serum insulin, previous history of GDM, obesity, BMI, age, and family history of diabetes." (PMID 38882352, 2024). "This suggests that the BB VDR genotype is a key factor in causing vitamin D deficiency." (PMID 38160213, 2024). "Therefore, this study aimed to evaluate the association between vitamin D deficiency, the VDR gene polymorphism FokI (rs2228570), and sleep quality." (PMID 38584183, 2024). "Moreover, mice with an AT specific deletion of the VDR mirror vitamin D-deficiency in humans and exhibit AT fibrosis and inflammation." (PMID 37063318, 2023). "Altered VDR expression or vitamin D deficiency may contribute to prostate cancer progression by disrupting these cellular processes." (PMID 37763224, 2023). "Myocardial fibrosis induced by vitamin D deficiency may be associated with decreased VDR expression, activation of the TGF-β1-Smad2/3 signaling pathway, and increased expression of profibrotic and inflammatory factors." (PMID 36771445, 2023). "In general, vitamin D deficiency is associated with a higher risk of infections and autoimmune diseases, involving dysfunctional biological activity of the specific vitamin D receptor (VDR), which is expressed in the majority of immunocytes." (PMID 36901976, 2023). "VDR gene knockout (VDR -/-) mice have been observed to have smaller muscle fibre sizes and to have significantly weaker grip strength than controls with similar effects observed due to diet-induced vitamin D deficiency." (PMID 36352180, 2023). "Indeed, vitamin D deficiency and polymorphisms of the vitamin D receptor (VDR) gene was associated with an increased risk of developing several autoimmune diseases, including hypothyroidism." (PMID 37635968, 2023).